IL9 (interleukin 9)
Diseases named in the same sentence as IL9 in open-access papers (continued):
Sharing a sentence is not in itself a finding about the gene and the disease.
tumor (continued). "In conclusion, these studies indicated that Th9 cells could act as effector T cells and directly kill tumor cells through the secretion of granzyme and IL-9." (PMID 32508847, 2020). "Finally, we demonstrated that recombinant IL-9 injection results in enhanced tumour control in dysbiotic mice." (PMID 32499569, 2020). "In addition, tumor-specific Th9 cells can eliminate advanced tumors, which depends on IL-9 and upregulated expression of Eomes and TRAF6." (PMID 32228589, 2020). "IL-9- and IL-9-producing cells have dual roles in tumor immunity." (PMID 32228589, 2020). "Further studies are warranted to obtain a comprehensive understanding of IL-9 and IL-9-producing cells in tumor immunity, which may contribute to finding more suitable targets for the clinical treatment of cancers." (PMID 32228589, 2020). "Our results indicate that antibiotic-induced dysbiosis negatively impacts Th9 and Tc9 cells in the lungs of tumour-challenged mice, indicating that IL-9-producing T cells may pose a significant contribution to microbiota-mediated tumour-immune surveillance." (PMID 32499569, 2020). "After PUUA treatment, silencing STAT5 or neutralizing IL-9 can promote tumor cell death." (PMID 32228589, 2020). "IL-9 in solid tumor cells always inhibits proliferation and promotes apoptosis of tumor cells." (PMID 32228589, 2020). "Neutralizing antibodies against IL-9 reversed this tumor-suppressive ability." (PMID 32228589, 2020). "Although IL-9-producing T cells have been described as potent antitumour effectors, their role in microbiota-mediated tumour control remains unclear." (PMID 32499569, 2020). "However, the authors reported that the anti-tumor effect of IL-1β-induced-Th9 cells relied on IL-21 since the neutralization of IL-9 had a minor impact on anti-tumor properties under this circumstance." (PMID 32508847, 2020). "In addition, there is evidence suggesting that IL-9 can promote the immunosuppressive function of Treg cells and protect tumor cells from the attack of immune cells." (PMID 32228589, 2020). "IL-33 can synergize with IL-3 to induce IL-9 production in human basophils, which may support tumor immunity." (PMID 33329534, 2020). "Since T-helper 9 (Th9) cell-derived IL-9 was verified to play a powerful antitumor role in solid tumors, an increasing number of researchers have started to pay attention to the role of IL-9-skewed CD8+ T (Tc9) cells, mast cells and Vδ2 T cell-derived IL-9 in tumor immunity." (PMID 32228589, 2020). "To further investigate the effects of Th9 and Tc9 cells in our model, we systemically injected recombinant IL-9 in dysbiotic animals, and found that it could partially protect against tumour burden." (PMID 32499569, 2020). "Moreover, the role of Th9 cells in eradicating advance tumor were also identified and suggested that IL-9, Eomes, and Traf6 of Th9 cells are essential in eradicating advance tumor." (PMID 31164892, 2019). "Furthermore, through regulated degradation of the transcription factor PU.1, autophagy has also been shown to limit Th9 differentiation, and T cells deficient in ATG3 or ATG5 show increased IL-9 production and improved IL-9-mediated tumor control." (PMID 31632966, 2019). "Moreover, IL-9 can also inhibit the apoptosis of tumor cells and promote their proliferation, as well as decrease the sensitivity of tumor cells to chemotherapeutic agents." (PMID 31414895, 2019). "In the current paper, we demonstrated that intravenous administration of DCG spores to TC-1 tumour bearing mice elicited strong splenic as well as tumour local immune responses, characterised by increased IFNγ or/and IL-9 secreting T cells in the spleen and the tumour site." (PMID 31183361, 2019). "Moreover, ILC2-derived IL-9 has recently gained attention in the context of tumor biology and has functional importance as growth factor for ILC2 and survival factor for other cell types." (PMID 32117199, 2019).
tumor (continued). "More recently, several studies highlighted anti-tumor properties of IL-9 producing CD4+ T cells." (PMID 31156634, 2019). "On the other hand, IL-9 secreted by Th9 cells could also promote the growth of some types of tumor cells, reflecting the complexity of its role in tumorigenesis." (PMID 31414895, 2019). "In these models, we observed that Il9 mRNA expression and IL-9 protein secretion were reduced in tumour-infiltrating CD4+ T cells (TILs) or in CD4+ T cells from tumour-draining lymph nodes (TDLN) of Irf8f/fCd4cre mice compared to those of WT or Irf8+/+Cd4cre mice." (PMID 29233972, 2017). "Furthermore, IL-9 can abolish the establishment of immunological memory to tumor re-challenge and exhibits an immunomodulatory role in pro-tumoral immunity." (PMID 28894450, 2017). "Importantly, inhibition of autophagy in TH9 cells enhances their anticancer functions in vivo, and mice with T cell-specific deletion of Atg5 have reduced tumour outgrowth in an IL-9-dependent manner." (PMID 28916785, 2017). "Accordingly, IL-9 enhances the anti-tumor activity of mast cells." (PMID 27832300, 2017). "In addition, IL-9 was proposed to enhance the immunosuppressive functions of Tregs and to block the establishment of adaptive anti-tumor immunity by preventing the development of immunologic memory." (PMID 27832300, 2017). "They found that neutralization of IL-9 abrogated the beneficial anti-tumor effect of DTA-1." (PMID 27832300, 2017). "Finally, the blockade of autophagy enhances TH9 cell anticancer functions in vivo, and mice with T cell-specific deletion of Atg5 have reduced tumour outgrowth in an IL-9-dependent manner." (PMID 28916785, 2017). "Accordingly, IL-9 drives tumor growth in most hematological cancers." (PMID 27832300, 2017). "Indeed, a blocking Ab against IL-9 when used in combination with CpG-ODN induces tumor eradication, supporting the plausible role of this cytokine in immune evasion by improving Treg function." (PMID 27049955, 2016). "Contrarily, IL9 has been reported to activate tumor immunity." (PMID 27655702, 2016). "Interestingly, adoptive transfer of anti-tumor TH9 cells inhibited tumor growth, and administration of an anti-IL-9 mAb reversed this effect." (PMID 27589682, 2016). "Furthermore, immunization of tumour-bearing mice with dectin-1-activated DCs induces potent antitumour response that depends on Th9 cells and IL-9 induced by dectin-1-activated DCs in vivo." (PMID 27492902, 2016). "Moreover, using a murine tumor model, these same investigators showed that adoptive transfer of tumor-reactive Th9 cells and administration of recombinant IL-9 can effectively reduce melanoma growth." (PMID 23533029, 2013). "However, the neutralization of IL-17 or depletion of MDSCs blunted such upregulation, suggesting that mast cells enhance Treg cells expressing IL-9 via IL-17 signaling pathway in tumor microenvironment." (PMID 20111717, 2010). "Moreover, the neutralization of IL-9 decreased the survival time of BMMCs in tumor microenvironment." (PMID 20111717, 2010). "Besides, prolonged antibiotic treatment by injection promotes ecological dysregulation of the host microbiota and heightens susceptibility to tumor formation, while FMT replenishes the diversity of the gut microbiota and IL-9 levels, ultimately suppressing tumorigenesis." (PMID 40177417, 2025). "Notably, exogenous rIL-9 inhibited tumor growth in Rag1(−/−) mice but not in mast-cell-deficient mice, indicating that IL-9 targets in this context include mast cells but not T or B cells." (PMID 41148223, 2025). "Notably, RORγ is also involved in tumor immunity through the regulation of IL-9 production." (PMID 39518891, 2024). "In addition, infiltration with IL-9+ cells might reflect the presence of an anti-tumor immune response actively suppressed through the PD-1/PD-L1 pathway." (PMID 37189417, 2023).
tumor (continued). "PD-1-driven regulation of IL-9 production by ILC2s may be relevant in cancer as PD-1+ ILC2s were detected in human cancer, and PD-1 blockade in combination with IL-33 enhanced the anti-tumor function of ILC2s." (PMID 37189417, 2023). "In certain tumor types, IL-9 may promote tumor growth and metastasis." (PMID 37425011, 2023). "The role of IL-9 in the tumor microenvironment and its effects on macrophages remains unclear." (PMID 35778404, 2022). "Therefore, we investigated if IL-9 would influence the tumor cell survival and death." (PMID 35514957, 2022). "However, growing evidence suggests that IL-9 can promote tumor growth in some contexts." (PMID 35778404, 2022). "Finally, antibodies to IL-9 inhibited tumor growth in vivo in two syngenic models of disease." (PMID 35514957, 2022). "Moreover, IL-9 promoted Arg1 expression from IMs isolated from tumor bearing mice ex vivo." (PMID 35778404, 2022). "However, in melanoma, IL-9 and Th9 cells have also shown anti-tumor activity." (PMID 35795670, 2022). "However, Th9 cells produce IL-21 in addition to IL-9, a cytokine with anti-tumor function." (PMID 35514957, 2022). "Together, these data suggest IL-9/IM/Arg1 axis may diminish the active anti-tumor immune response." (PMID 35778404, 2022). "However, understanding of how IL-9 might contribute to tumor growth and which cells are important in the tumor microenvironment for mediating those effects is still very limited." (PMID 35778404, 2022). "In the present study, HNSCC tumor-infiltrating lymphocytes (TILs), which secrete typical cytokines associated with Th1-, Th2-, Th9-, Th17-, and Th21-polarized inflammation (including IFN-γ, IL-4, IL-9, IL-17, and IL-21), were identified using flow cytometric analysis." (PMID 34026621, 2021). "In conclusion, this study deciphers the molecular pathway involved in the regulation of IL-9 induction in Th cells and its subsequent implication in Th9 cell-mediated anti-tumor immune response, which could be potentially targeted for successful cancer immunotherapy." (PMID 34075041, 2021). "Finally, recombinant IL-9 injection enhances tumour control in dysbiotic mice." (PMID 32499569, 2020). "Given the fact that the host microbiota were important for the differentiation of both Th9 and Tc9 cells in the colonic lamina propria, we next sought to evaluate whether a long-term antibiotic treatment would impair IL-9-producing T cells in an extraintestinal tumour model." (PMID 32499569, 2020). "Therefore, the full mechanism of IL-9 in tumor immunity needs further study." (PMID 32228589, 2020). "In addition, adoptive transfer of Tc9 cells can produce a strong antitumor effect in the MC38-GP100 tumor model, and this effect could be reversed by anti-IL-9." (PMID 32228589, 2020). "Interestingly, our results showed that a mixed IL-9/IFNγ secreting T cell response was induced when the tumour bearing mice received a low dose of DCG spore (1 × 108 CFU/kg), while a strong IFNγ response was elicited with a high dosage of DCG spore (3 × 108 CFU/kg)." (PMID 31183361, 2019). "We wondered if the IL-9-producing cells could be induced in tumor-bearing mice by immunotherapy." (PMID 28002799, 2017). "It remains to be determined whether this effect is relevantin vivo, but in this regard, IL-1β could induce the production of high levels of IL-21 by Th9 cells, but these cells nevertheless continued to produce IL-9 and acquired potent IL-21-mediated anti-tumor activity." (PMID 29123649, 2017). "Thus, in tumor immunity, the exact immunological roles of IL-9-producing Vγ9Vδ2-T cells are still unknown." (PMID 28894450, 2017). "Moreover, tumor-specific IL-9-producing CD8+Tc9 cells also exert potent anti-tumor effects." (PMID 27589682, 2016). "However, IL-9R expression is increased in EL-4 cells, indicating an additional effect of IL-9 on tumor cells; evaluation of IL-9R expression may therefore be critical for IL-9 anti-tumor therapy." (PMID 27589682, 2016).
tumor (continued). "Given that Treg cells produce IL-9 for immune suppression through the activation of mast cells in an allograft model, and that IL-9 plays an important role in mast cell survival, we here further speculated that the involvement of IL-9 by Treg cells in mast cell-mediated tumor promotion." (PMID 20111717, 2010). "IL‐9/STAT3 axis upregulated fatty acid oxidation and mitochondrial activity that impeded the lipid peroxidation overload in Tc9 cells and resistance to tumour or ROS‐induced ferroptosis in the TME." (PMID 40045458, 2025). "Analysis of cytokine secretion over 21 d post CAR T cell infusion revealed elevated levels of IFN-gamma and IL-9 at day 7 in the FOLR1 CAR T-treated group bearing OV-90 wt xenografts, which correlated with anti-tumor function." (PMID 38254822, 2024). "Plasma IL-9 represents a potential predictive biomarker of NAC-ICI response, while tumor IL-8 signature and stroma-rich subtype represent potential predictive biomarkers of response benefit of NAC-ICI over neoadjuvant ICI." (PMID 38789460, 2024). "Another study indicated low expression of IL-9 in CRC tissues and suggested an anti-tumorigenic effect of IL-9 through the facilitation of CD8 + T cell infiltration and the creation of an anti-tumor microenvironment." (PMID 38741166, 2024). "Although the different functions of IL-9 are still under debate, we observed a temporary increase in IL-9 on day 7 post CAR T cell injection, correlating with better anti-tumor responses of candidates A and E." (PMID 38254822, 2024). "On one hand, IL-9 correlates with lower amounts of IL-4, IL-10, VEGF, and TGF-β, which are important for tumour growth." (PMID 38920685, 2024). "Various genes with tumor suppressor functions, such as chemokine ligand-11, IL-21, IL-27, CD40L, chemokine ligand-9, IL-9, and IL-15, were upregulated in DBMSCs after treatment with MDA231 cells in an IC setting." (PMID 39768220, 2024). "Prior to conducting the assay, we identified a subset panel of factors known to mediate the induction of apoptosis in tumor cells: IL-27, IL-1b, IL-2, CXCL10, IL-12p70, G-CSF, IFN-g, TNF-a, IFN-a, CCL2, IL-9, TNF-b, TRAIL, IL-18, IL-21, TSLP." (PMID 37468934, 2023). "Even though just a few nanograms of IL9 were secreted by the B16F10-IL9 mice per day, the consistent and even distribution of IL9 in the tumor area resulted in a strong antitumor response." (PMID 36968220, 2023). "Treatment of tumor-bearing mice with an agonistic anti-GITR antibody induced TH9 cells and the efficacy of the treatment was remarkably reduced with the blockade of IL-9." (PMID 37189417, 2023). "Although IL-9 expression was reduced by day 7 post-transfection, it was upregulated again in PB CAR-T cells upon encountering tumor cells." (PMID 37228617, 2023). "Different tumor cell-dependent and TME-dependent factors can contribute to IL-9 production and accordingly affect the response to anti-PD-1 treatment." (PMID 37189417, 2023). "In the context of cancer, the type 2 cytokines IL-4, IL-5, IL-9, and IL-13 along with ILC2s, Th2, and Th9 cells may either promote or inhibit tumorigenesis in a context-dependent manner that involves complex interactions with cancer cells and the constituents of the tumour microenvironment." (PMID 37455828, 2023). "Overexpression of IL-9 by the CT26 CRC cell line genetically led to enhanced CD4+ and CD8+ T cell recruitment resulting in heightened serum INFγ and tumour lysis." (PMID 37455828, 2023). "Second, to compare the cytotoxic effect of IL9-polarized macrophages, rIL9 and PBS-treated BMDMs were used as effector cells while B16F10 tumor cells were used as the targets." (PMID 36968220, 2023). "Conversely, mast cells possess the capacity to combat tumors directly via tumor cell cytotoxicity induced by TNF-a and ROS or indirectly through the synthesis of interleukin-9 and heparin and the initiation of dendritic cell maturation." (PMID 37256127, 2023).
tumor (continued). "Mechanistic studies revealed that the IL-9/STAT3/fatty acid oxidation pathway rendered Tc9 cells with reduced lipid peroxidation and resistance to tumor- or ROS-induced ferroptosis in the TME." (PMID 35192544, 2022). "We demonstrate that IL-9 expression is augmented in NSCLC and plays an important functional role in regulating tumor cell growth." (PMID 35514957, 2022). "The Th17 cells were converted into cells that mediate IL-9-dependent effects by STAT5 and BATF in allergic airway inflammation and anti-tumor immunity." (PMID 36138889, 2022). "Intercompartmental IL9 and IL18 gradients were assessed in matched samples of tumor epithelium, stroma, and serum of patients." (PMID 36131941, 2022). "To consider the role of spatial concentrations and gradients of IL9 and IL18, we investigated the tumor-to-stroma and stroma-to-serum gradients of IL9 and IL18 in our patient cohort." (PMID 36131941, 2022). "Lung macrophages were isolated from tumor bearing mice and plated in the lower chamber of the plate with PBS or IL-9." (PMID 35778404, 2022). "In this report, we systematically review the precise roles of IL-9, IRF-8, and AP-1 in tumor development, particularly with regard to DLBCL." (PMID 35211408, 2022). "In summary, the present study has uncovered an important pro-tumoral role of IL-9 in NSCLC via direct effects on tumor cells and modulation of cytokine production by tumor infiltrating T cells." (PMID 35514957, 2022). "In subsequent studies on the effects of anti-IL-9 antibodies in experimental NSCLC, we explored the effects of these antibodies at later time points of tumor induction in the two models of disease in syngenic mice." (PMID 35514957, 2022). "Additionally, tumor-associated macrophages (TAMs) in mouse lungs were shown to be tissue-resident IM and CCR2-dependent recruited macrophages, with the former mainly promoting tumor growth in—among others- an IL-9-dependent manner, and the latter facilitating tumor cell dissemination." (PMID 36305904, 2022). "By contrast, expression of Il9 and Il4, known cytokine inducers of MMC and CTMC respectively, showed a marked IL-33 dependent increase in gp130F/F antral tumours, with levels in gp130F/FIl33−/−compound mutants comparable to those of WT controls." (PMID 35677533, 2022). "Densitometry analysis showed that five cytokines, IL-4, AXL, IL-1β, IL-9, Exotaxine-2 and IL2, were upregulated, and two cytokines, PF4 and IL-6, were downregulated in the tumor environment of JEG3-Sh-NLRP7 cells." (PMID 34203890, 2021). "Levels of IL-9 and IL-27 were higher in the LNME compared to the TME, with both having mixed or tumour-promoting effects in terms of cancer progression." (PMID 34439160, 2021). "In this neoplasia, the activation of IL-9-dependent autocrine/paracrine loops results in amplified JAK/STAT signaling and enhanced tumor cell survival and proliferation." (PMID 34944921, 2021). "Inhibition of EGFR suppressed the IL-9 induction in all Th cells and our data indicates that EGFR pathway is crucial for the anti-tumor functions of Th9 cells." (PMID 34075041, 2021). "Th9 cell-derived IL-9 and IL-21 further enhance the ability of CTL and NKT cells to secrete IFN-γ, thereby promoting tumor cell killing." (PMID 34944921, 2021). "The activation of the maternal immune system leads to an increase in the release of cytokines such as, IL-1β, IL-9, IL-17, Eotaxin-2 and IL2 in the tumor environment and subsequently in the maternal circulation." (PMID 34203890, 2021). "Quantitative analysis of tumor RNA regarding specific cytokines for mast cells recruitment such as IL4 and IL9 confirmed our observations." (PMID 33086657, 2020). "Many other cells can secrete IL-9, such as NKT cells and ILC2s, but their role in tumor immunity is unclear." (PMID 32228589, 2020). "Antigen-specific IL9-secreting CD4 Th9 and CD8 Tc9 cells have been previously characterized for their anti-tumour properties." (PMID 33214555, 2020).